TXNDC9 (thioredoxin domain containing 9)
Description:
Significantly diminishes the chaperonin TCP1 complex ATPase activity, thus negatively impacts protein folding, including that of actin or tubulin.
Synonyms: APACD; PHLP3
Tractability: PROTAC: ubiquitination databases record sites on it; its protein half-life has been measured.
Gene: Protein-coding gene on chromosome 2 (99,318,982 to 99,340,702, reverse strand). Ensembl gene ENSG00000115514.
Subcellular location: Cytoplasm; Nucleus; Cytoplasm, cytoskeleton, microtubule organizing center, centrosome; Midbody
Subcellular location (Human Protein Atlas): Cytosol
Gene Ontology:
Molecular function: cadherin binding; protein binding
Biological process: microtubule cytoskeleton organization
Cellular component: cytosol; cytoplasm; midbody; nucleus; centrosome
Genetic constraint (gnomAD): Loss-of-function variants: 4 observed, 17.76 expected, observed/expected ratio (o/e) 0.23, 90% interval 0.11 to 0.51. The upper end of that interval is the gene's LOEUF score, 0.51, which puts it in group 2 of 6, group 1 being the genes least tolerant of losing a copy. Missense variants: 182 observed, 235.46 expected, observed/expected ratio (o/e) 0.77, 90% interval 0.68 to 0.87. Synonymous variants: 66 observed, 86.86 expected, observed/expected ratio (o/e) 0.76, 90% interval 0.62 to 0.93.
Homologues: Orthologues: chimpanzee TXNDC9 (99% identical), macaque TXNDC9 (96% identical), dog TXNDC9 (95% identical), pig TXNDC9 (95% identical), guinea pig TXNDC9 (95% identical), mouse Txndc9 (90% identical), rat Txndc9 (89% identical), tropical clawed frog txndc9 (79% identical), zebrafish txndc9 (72% identical), Drosophila melanogaster CG4511 (51% identical), Caenorhabditis elegans txdc-9 (39% identical). Paralogues in human: PDCL2 (27% identical), PDCL3 (25% identical), PDCL (18% identical), PDC (17% identical).
Diseases named in the same sentence as TXNDC9 in open-access papers:
TXNDC9 is named in the same sentence as 14 diseases in open-access papers, as found by Europe PMC text mining. Sharing a sentence is not in itself a finding about the gene and the disease. The quoted sentences say what the papers report.
glioma (4 papers, 2020 to 2024). A benign or malignant brain and spinal cord tumor that arises from glial cells (astrocytes, oligodendrocytes, ependymal cells). "In this study, we stated that TXNDC9 would be a tumor-associated gene, which involved in the development of glioma." (PMID 32897242, 2020). "Meanwhile, TXNDC9 promotes the progression of hepatocellular carcinoma and prostate cancer and regulates apoptosis and autophagy in glioma and colorectal cancer." (PMID 37686174, 2023). "Knockouts of the TXNDC9 gene can inhibit the proliferation and metastasis of glioma cells and induce apoptosis of glioma cells." (PMID 34629960, 2021). "To explore the role of TXNDC9 in glioma, we first detected the expression of TXNDC9 in glioma tissue and normal tissue." (PMID 32897242, 2020). "Then we measured the mRNA and protein level of TXNDC9 in different human glioma cell lines (LN18, U87, U118, T98, U251) and human astrocytes (NHA) was used as a control." (PMID 32897242, 2020). "As another member of the thioredoxin family, TXNDC9 is upregulated in gliomas." (PMID 34629960, 2021). "Cell morphology and expression analysis of GFAP, Vimentin, verified that TXNDC9 could regulate glioma cell differentiation." (PMID 32897242, 2020). "In our study, we found that TXNDC9 can affect the differentiation of glioma cells." (PMID 32897242, 2020). "In this study, we found the up-regulated of TXNDC9 in U87 and U251 glioma cells." (PMID 32897242, 2020). "In this study, for the first, the function of TXNDC9 was revealed in glioma cells." (PMID 32897242, 2020). "Compared with NHA, the expression of TXNDC9 was up-regulated in all glioma cell lines." (PMID 32897242, 2020). "In this study, we found that TXNDC9 was upregulated in glioma." (PMID 32897242, 2020). "The expression and function of TXNDC9 in glioma cells have not been reported." (PMID 32897242, 2020).
hepatocellular carcinoma (4 papers, 2018 to 2023). A malignant tumor that arises from hepatocytes. "In hepatocellular carcinoma, recent studies have demonstrated that TXNDC9 promotes cancer progression by mediating the gene regulation networks." (PMID 37303736, 2023).
colorectal cancer (3 papers, 2018 to 2025). A primary or metastatic malignant neoplasm that affects the colon or rectum. "Interestingly, recent studies have demonstrated that TXNDC9 was overexpressed in colorectal cancer, indicating a potential oncogenic function of TXNDC9 in malignant diseases." (PMID 30382079, 2018).
colorectal adenocarcinoma (2 papers, 2023). The most common type of colorectal carcinoma. "Regarding genes in this analysis, TXNDC9 was reported to be upregulated upon oxaliplatin treatment and may confer oxaliplatin resistance in colorectal adenocarcinoma cells." (PMID 36839749, 2023).
cutaneous squamous cell carcinoma (1 paper, 2025). "TXNDC9’s modulation of NF-κB/p65 signaling in cutaneous squamous cell carcinoma also warrants evaluation as a therapeutic target." (PMID 41009046, 2025).
squamous cell carcinoma (1 paper, 2025). A carcinoma arising from squamous epithelial cells. "Recently, it was found that UV-B-irradiated squamous-cell carcinoma cells exploit Thioredoxin domain-containing protein 9 (TXNDC9) to facilitate IκBα phosphorylation and p65 translocation, promoting survival; knocking down TXNDC9 restores apoptosis and impairs NF-κB activation." (PMID 41009046, 2025).
cancer (5 papers, 2018 to 2025). A tumor composed of atypical neoplastic, often pleomorphic cells that invade other tissues. "Trend analysis of HSP90 and TXNDC9 expression in individual CRC samples within the TCGA database demonstrated highly similar expression patterns in the cancer tissues of CRC patients." (PMID 40184625, 2025). "Five—Using STRING database, we found that it had interactions with several proteins involved in different cancers such as TXNDC9, GXYLT2, POFUT1, XXYLT1, FLNA, and ZC3H12C." (PMID 35140741, 2021). "TXNDC9 is a critical regulator in cell proliferation in some types of cancers." (PMID 37303736, 2023). "Ablation of TXNDC9 significantly reduced the cancer phenotype of HCC." (PMID 30382079, 2018). "The results indicated markedly elevated levels of TXNDC9 and HSP90AA1 expression in the cancer tissues of CRC patients compared to their adjacent noncancerous tissues." (PMID 40184625, 2025).
tumor (4 papers, 2018 to 2025). "High TXNDC9 expression was positively correlated with tumor-node-metastasis (TNM) stage (p = 0.035)." (PMID 30382079, 2018). "In this study, we also demonstrated that TXNDC9 was over-expressed in HCC and associated with a larger tumor, poor histological type, and higher TNM stage." (PMID 30382079, 2018). "TXNDC9 belongs to thioredoxin domain-containing proteins, which is involved in tumor progression." (PMID 32897242, 2020). "Knockdown of TXNDC9 could prevent tumor program, induce apoptosis, and autophagy in U87 and U251 cells." (PMID 32897242, 2020). "In addition, we also observed that positive TXNDC9 expression was significantly related to tumor size > 5 cm (p = 0.013) and poor tumor differentiation (p = 0.022)." (PMID 30382079, 2018). "Univariate Cox regression analysis indicated that multiple tumors (p = 0.014), tumor size > 5 cm (p = 0.008), portal vein invasion (p = 0.007), poor tumor differentiation (p = 0.018), TNM stage III–IV (p = 0.001), and positive TXNDC9 expression (p = 0.011) were predictors for a lower OS." (PMID 30382079, 2018).
infection (1 paper, 2025). The state of being infected such as from the introduction of a foreign agent such as serum, vaccine, antigenic substance or organism. "Western blot and qRT‐PCR analysis revealed a substantial increase in the TXNDC9 protein level following infection in the OE group, and the TXNDC9 level was decreased in the siRNAs‐transfected cells (***P < 0.001)." (PMID 40184625, 2025).
TXNDC9 also shares sentences with these, for which no sentence is quoted: prostate carcinoma (3 papers); Cirrhosis (1); colorectal tumor (1); head and neck squamous cell carcinoma (1); malignant glioma (1).